LOX (lysyl oxidase)
Diseases named in the same sentence as LOX in open-access papers (continued):
Sharing a sentence is not in itself a finding about the gene and the disease.
breast carcinoma (continued). "We co-treated breast cancer cells MDA-MB-231 (with high LOXL1 and BAG2 expression) with HSP90 inhibitor (IPI-504), HSP70 inhibitor (VER-155008), LOX inhibitor (BAPN), or NAMPT (FK886) inhibitor and doxorubicin, and we observed the survival rate to calculate the drug interactions." (PMID 40426862, 2025). "Additionally, LOX has been found to facilitate the formation of ECM adhesions and inhibit the migration of invasive breast cancer cells." (PMID 37469162, 2024). "Additionally, programmed cell death protein-4 (PDCD4) has been shown to decrease LOX expression in a HIF-independent manner, thereby mitigating the migration and invasion of breast cancer cells." (PMID 39247609, 2024). "The results showed that LOX and LOXL2 are critical for the growth of breast cancer cells." (PMID 38672570, 2024). "In breast cancer, inhibition of ATP7A disrupts LOX activity and impedes metastasis." (PMID 38662225, 2024). "For instance, in breast cancer and head and neck tumour cells, hypoxia-induced HIF-1α interacts with the hypoxia-inducible element (HRE) of LOX, thereby enhancing the transcription and expression of LOX." (PMID 39247609, 2024). "Moreover, LOX, MMP-2, and MMP-9 are more highly expressed in breast cancer tissues with axillary lymph node metastasis, suggesting a potential synergistic role in breast cancer metastasis." (PMID 39247609, 2024). "Moreover, the invasion and aggression of breast cancer were accompanied by extracellular matrix (ECM) stiffness and immune cell infiltration /coupled with lysyl oxidase (LOX)–mediated collagen cross-linking." (PMID 35138531, 2023). "For example, magnolol can inhibit the expression of lysyl oxidase from disrupting FAK/Src/paxillin signaling to inhibit the migration and invasion of breast cancer cells, which is considered to be an ideal strategy for breast cancer treatment." (PMID 37175948, 2023). "Consequently, LOX and LOXL1–4 enzymes have been suggested as potential druggable targets to prevent breast cancer metastasis." (PMID 35800439, 2022). "CAFs-derived lysyl oxidase (LOX) functions as the initiator of collagen crosslinking in overexpression in several cancers, such as gastric and breast cancer and promoting cancer cell survival, epithelial–mesenchymal transition (EMT), metastasis, invasion, angiogenesis, and drug resistance." (PMID 35327514, 2022). "Together, these studies suggest that targeting of LOX may be a novel strategy to reduce ECM stiffness and potentially improve outcomes in breast cancer patients with obesity." (PMID 35435599, 2022). "In addition, paclitaxel chemotherapy can enhance rapid ECM remodeling and mechano-structural changes by inducing the expression of LOX in CD8+ T cells, subsequently improving the invasion and metastasis of breast cancer cells in the lung." (PMID 36293126, 2022). "LOX, MMP2, MMP3, MMP9, RHOA, VIM gene panel expression monitoring was considered because they are correlated with a more aggressive and invasive phenotype in breast cancer cells." (PMID 33543395, 2021). "In addition, hypoxia has been shown to induce lysyl oxidase (LOX) and LOX-like proteins (LOXL) secretion by breast cancer cells." (PMID 34202979, 2021). "LOX inhibition (through BAPN) not only reduced collagen crosslinking and fibronectin assembly but also increased drug penetration and re-sensitized tumors to doxorubicin treatment in breast cancer, and enhanced sensitivity to radiotherapy in prostate cancer." (PMID 34298680, 2021). "LOX pharmacological inhibition using BAPN or an anti-LOX antibody prior to surgical intervention was able to reduce lung metastasis after surgery and increased animal survival in a murine model of breast cancer." (PMID 33669630, 2021). "Moreover, the collagen cross-linking and ECM stiffening mediated by Lysyl oxidase (Lox) was shown to induce both Y397 FAK phosphorylation and FAs formation, thereby promoting the growth and invasion of an oncogene-initiated mammary tumor." (PMID 33562737, 2021).
breast carcinoma (continued). "Lysyl oxidase (LOX) and MMP inhibitors were evidenced to regulate the extracellular matrix remodeling, improving the drug delivery efficacy in in vitro and in vivo breast cancer models." (PMID 33352766, 2020). "β-aminopropionitrile (BAPN), an irreversible inhibitor of catalytic activity of LOX and LOX1-4, has been shown to exert a suppressive effect on metastatic colonization of circulating breast cancer cells, hypoxia-induced invasion of cervical cancer cells, and the angiogenic capacity of HUVEC." (PMID 33371259, 2020). "For example, TNF-α induces LOX expression via the reactive oxygen species-activated nuclear factor-kappaB (NF-κB)/extracellular signal-related kinase (ERK) pathway, thus promoting the progression of breast cancer metastasis." (PMID 33123472, 2020). "Furthermore, we propose that CTGF is a versatile regulator in breast cancer and facilitates SPARC, LOX, ZEB1, VIM and FN1 expression changes." (PMID 33087801, 2020). "Although CXCL12, CCL2, VEGF, MMP2, LOX, and CXCR4 were highly associated with HIF-1α expression, their prognostic significance in breast cancer is less so they were not chosen for further immunohistochemistry analyses." (PMID 33003428, 2020). "This could be due to the lower expression of LOX enzymes seen in the ERK5-ko RNA sequencing analysis, a protein that is correlated with metastasis in breast cancer." (PMID 32850332, 2020). "The results revealed that LOX-targeted nanoparticles were more effective when compared to a soluble anti-LOX antibody (which was not accompanied by nanoparticles) in vitro in mouse mammary cancer cells and in vivo in a mouse breast cancer xenograft model." (PMID 32042347, 2020). "We analyzed impact of CTGF on other secretome analysis detected targets and could detect that reducing CTGF expression represses TGFBI, LOX and ZEB1 expression in mesenchymal transformed breast cancer cells." (PMID 33087801, 2020). "High LOX expression levels have been shown in invasive basal breast cancer, but not in non-invasive ductal breast cancer, and are associated with increased metastasis and decreased survival in breast cancer patients." (PMID 31130685, 2019). "Our systematic investigation of effect of hypoxia on breast cancer cell assembly and gene expression within 3D culture showed hypoxia enhanced EMT, increased LOX expression and activity, and migration onto lung mesenchymal cells (LMC, derived from the same patient) laden hydrogel." (PMID 30181809, 2018). "The curative effect of bisphosphonates on breast cancer is also mentioned in recent publications discussing potential options for the treatment of lysyl oxidase positive, estrogen receptor negative (LOX+, ER−) breast cancer patients." (PMID 28914765, 2017). "Overexpression of lysyl oxidase (LOX) is often observed in estrogen receptor negative (ER–) breast cancer patients with bone metastasis." (PMID 27147578, 2016). "Most studies have been conducted in various breast cancer models to assess potential roles of the LOX enzyme family as molecular targets in the development of novel therapeutic drugs." (PMID 26265048, 2015). "Moreover, the tumour suppressor activity of LOX is executed, at least in part, by the pro-peptide, which inhibited tumour formation and the invasiveness of HER2/neu driven NF639 breast cancer cells." (PMID 25141126, 2014). "LOX itself has recently been argued to be a promising cancer therapeutic target, and we consider LOX high/ER negative patients as a suitable collective for the initial breast cancer trials if in place." (PMID 25141126, 2014). "Additionally, when we tested the ability of another highly metastatic breast cancer cell SK-BR-3 to induce HIF-1α expression and LOX release, SK-BR-3 dramatically induced HIF-1α expression and LOX release by hypoxia." (PMID 25238333, 2014).
breast carcinoma (continued). "In addition, P2Y2R activation by ATP in breast cancer cells induces HIF-1α expression, LOX secretion, and collagen crosslinking, which forms a receptive microenvironment for pre-metastatic niche formation." (PMID 25238333, 2014). "In summary, here LOX-PP is shown to interact directly with CIN85 via an atypical ligand thereby reducing interaction of CIN85 with c-Cbl, and reducing the invasive phenotype of breast cancer cells." (PMID 24167568, 2013). "More specifically, it has been shown that HIF-1α may induce an enhanced expression of lysyl oxidase (LOX), lysyl oxidase-like 2 (LOXL2) and LOXL4 in hypoxic breast cancer cells within primary breast tumour." (PMID 23301832, 2013). "We therefore evaluated the ability of the irreversible LOX inhibitor, β-aminopropionitrile (BAPN), to regulate metastatic colonization and growth of the MDA-MB-231 breast cancer cells following their introduction into the arterial circulation of immunodeficient mice." (PMID 19440335, 2009). "This is not surprising in view of the fact that in MCF-7, MCF-10, and MDA-MD-231 breast cancer cells, LOX, but not COX inhibitors, blocked EGF/transforming growth factor-α stimulation of 12-HODE and 13-HODE production and cellular proliferation." (PMID 18087590, 2007). "LOXL2, a member of the lysyl oxidase (LOX) family, is overexpressed in multiple human malignancies including gastric cancer, hepatocellular carcinoma, breast cancer, and squamous cell carcinoma, where it correlates with aggressive clinicopathological features and poor prognosis." (PMID 41357999, 2025). "We speculate that while the impact of LOXL3 inhibition may vary with breast cancer subtype, the therapeutical inhibition of LOX, LOXL1 and LOXL2 but not of LOXL4 may be the most beneficial." (PMID 35800439, 2022). "Inhibition of the collagen-crosslinking lysyl oxidase (LOX) family in mice decreased fibrosis as well as tumor incidence and tumor size in a mouse model, and high lysyl oxidase-like 2 (LOXL2) expression correlates with low overall and metastasis-free survival in breast cancer patients." (PMID 33534863, 2021). "This was in contrast with the expression of known HIF target genes involved in breast cancer metastasis not included in the hypoxia signatures (LOX, LOXL2, LOXL4, CCL2, L1CAM, ANGPT1, and ANGPT2), whose expression showed a positive correlation with the signatures." (PMID 29540773, 2018). "With respect to molecular mechanistic studies of Cu proteins’ roles in breast cancer, there is such information reported for ten proteins and below we discuss findings for selected proteins of the ten (MEMO1, SPARC, LOX, and some LOX-like proteins), followed by a separate section about ATOX1." (PMID 28425924, 2017). "Notably, LOX-PP attenuates fibronectin-mediated integrin signaling via the focal adhesion kinase (FAK) - p130Cas pathway, and selectively inhibits integrin-mediated migration of breast cancer cells." (PMID 24167568, 2013). "Moreover, the inhibition of LOX, which is induced by HIF-1α in hypoxic breast cancer cells at primary tumours by shRNA, was also effective at preventing the CD11b+ BMDC recruitment, pre-metastatic niche formation and metastatic growth of MDA-MB-231 breast cancer cells at lungs in a mouse model." (PMID 23301832, 2013). "Conversely, in breast cancer, the GATA-3 transcription factor acts as a negative regulator by promoting the methylation of the LOX promoter, consequently reducing LOX expression." (PMID 39247609, 2024). "To determine the clinical relevance of LOX expression in chemotherapy-treated TNBCs, we performed survival analyses and observed that higher LOX mRNA expression predicts poor RFS only in chemotherapy-treated basal breast cancer patients, but not in other breast cancer subtypes or in untreated cases." (PMID 32415208, 2020).
melanoma (52 papers, 1994 to 2025). A malignant, usually aggressive tumor composed of atypical, neoplastic melanocytes. "LOX is a tumor suppressor gene, which when mutated in SCs, can suppress T-cells in the melanoma tumor microenvironment." (PMID 40585242, 2025). "This was first evidenced by its identification in the invadopodia of melanoma LOX cells, where FAPα, initially termed “seprase”, was associated with gelatinolytic activity, underscoring its role in matrix degradation during melanoma invasion." (PMID 40918451, 2025). "In the same study, other genes such as COL5A1, periostin (POSTN), thrombospodin 2 (THBS2) and LOX were upregulated and associated with poor survival after adjuvant chemotherapy; these genes were also upregulated in our melanoma case series." (PMID 28743863, 2017). "For the development of radiotracers that enable PET imaging of the melanoma-associated lysyl oxidase activity, substrates derived from the type I collagen α1 N-telopeptide were labeled with fluorine-18 using N-succinimidyl 4-[18F]fluorobenzoate ([18F]SFB) as prosthetic reagent." (PMID 29755969, 2018). "An alternative spliced FAP-α was later identified in the human melanoma cell line LOX which encodes a truncated isoform which encodes a 239 amino acid polypeptide with a molecular weight of 27 kDa that precisely overlaps the carboxylterminal catalytic region of the wild type FAP-α." (PMID 24885257, 2014). "While undetectable in melanocytes and primary melanoma cells, LOX up-regulation was described in metastatic BLM cells and in the vertical growth phase of the WM793 melanoma cell line." (PMID 38247872, 2024). "We chose LOX Melanoma cells for these studies as this line appears more tolerant of variant sequences." (PMID 38824190, 2024). "We then assessed the effect of MITF silencing on miR-579-3p, ZFR and TYR expression levels in three different melanoma cell lines (i.e. LOX IMVI, WM266 and M14)." (PMID 38472212, 2024). "Since LOX and the LOX family members (LOXL 1-4) are expressed and up-regulated in melanoma, we investigated LOX gene expression in our experimental models." (PMID 38247872, 2024). "For our future work, the same screening will be repeated on other human melanoma cell lines, such as LOX IMVI and MALME-3M, to confirm if the observations/mechanisms of action are the same for multiple human melanoma cell lines." (PMID 36661500, 2022). "Compounds 17a-c were highly active against LOX IMVI (melanoma), with IC50 values of 0.34, 0.73 and 0.54 μM, respectively." (PMID 36293443, 2022). "The cytotoxic polyacetylenes isolated from Dendropanax arboreus described in Section 2.1.2 have also been investigated for their in vivo activity in a murine LOX melanoma xenograft model." (PMID 32486470, 2020). "All tested polyacetylenes showed modest activity but still some potential for in vivo antitumor activity with dehydrofalcarinol having the greatest activity in the employed LOX melanoma model showing the best effect at a concentration at 3 mg/kg." (PMID 32486470, 2020). "We further show that the invasive growth of melanoma cells can be inhibited with ΒAPN, and even totally blocked by depletion of LOX and LOXL2 with shRNAs." (PMID 30701028, 2018). "Here, we found that also the expression of LOX, LOXL1, and LOXL3 encoding proteins that crosslink ECM proteins (collagens and elastin) are increased in many melanoma cells and primary melanomas." (PMID 30701028, 2018). "To resolve this paradox, we further studied the functions of the encoded proteins by using a universal LOX inhibitor Β-aminopropionitrile (BAPN) and knocking down of LOX and LOXL2 in melanoma cells." (PMID 30701028, 2018). "LOX was expressed at the level of assay sensitivity only in the vertical growth phase melanoma cell line WM793 and in the metastatic cell lines BLM and SK-MEL-147." (PMID 30701028, 2018).
melanoma (continued). "The protein expression of LOXL2, in turn, was abundant in both HES and the melanoma cells, and varied less than that of LOX, with SK-MEL-147 showing the lowest expression." (PMID 30701028, 2018). "We further used fluorescent labeling of melanoma cells (red) and fibroblasts (green) to differentiate the effect of LOX inhibition on the two cell types in the co-cultures." (PMID 30701028, 2018). "A mouse model of human melanoma was established on the basis of the A375 cell line, for which the expression of the oncologically relevant lysyl oxidase isoforms LOX and LOXL2 was demonstrated in Western blot and immunohistochemical experiments." (PMID 29755969, 2018). "HIF-1 signaling is important for pre-metastatic niche formation via lysyl oxidase (LOX) (lung metastases) and tumor-lymphatic vessel cross-talk to support metastasis colonization in breast, melanoma, prostate, gastric, and colon cancer patients." (PMID 27187355, 2016). "We used human LOX melanoma cells for this analysis because their very long telomeres (mean telomere length ∼50 kb) allow better linear resolution." (PMID 26640040, 2015). "As this cell line does not express YKL-40, this indicates that the observed effect for the LOX tumors was indeed human YKL-40 (secreted by the melanoma cells) specific." (PMID 24752554, 2014). "Treatment of the melanoma cell line LOX for 24 h led to reductions of endogenous S1P levels with an IC50 of 7.5 μM." (PMID 23861887, 2013). "We first utilized Q-MSP to determine the methylation status of the 14-3-3σ gene in NHEM and several established melanoma cell lines, including A375, C8161.9, LOX and WM-266-4." (PMID 19473536, 2009). "The extent of lectin binding by three human melanoma (LOX, FEMX-1 and SESX) and two sarcoma lines (MHMX and OHSX) was related to their potential for experimental metastasis formation in athymic nude mice." (PMID 8198963, 1994). "Finally, TGF-β1, a master controller of EMT, and lysyl oxidase (LOX), involved in melanoma progression, were strongly up-regulated by 3D arrangement in the metastatic BLM cells alone, likely playing a role in the metastatic phases of melanoma progression." (PMID 38247872, 2024). "Hence, further studies are needed to clarify the specific roles of the different LOX proteins in the collaborating cells regulating melanoma cell behavior." (PMID 30701028, 2018). "On the contrary, LOX and especially LOXL2, LOXL3, and LOXL4 were found to be upregulated in several human melanoma cell lines, and LOX inhibitor B-aminopropionitrile inhibited the invasive growth of these cells particularly when co-cultured with fibroblasts in Matrigel." (PMID 30701028, 2018). "As a biological example, we chose to investigate a Vemurafenib resistant melanoma cell line, LOX-IMVI, as compared to a sensitive cell line A375 with the goal of implicating mutations that may be affecting LOX-IMVI’s response to the drug." (PMID 29023449, 2017). "To prove specificity, we used stable transfected LOX melanoma cell clones." (PMID 28698473, 2017). "Worthy of note is also the upregulation of LOX in our malignant melanoma samples." (PMID 28743863, 2017). "While mRNA profiling suggests that Bfl-1 confers apoptotic resistance in SK-MEL-5 and LOX-IMVI melanomas, our combinatorial antagonism of pro-survival homologs indicates that Mcl-1 plays a more critical role and further discriminates between sensitive LOX-IMVI and resistant SK-MEL-5." (PMID 27805565, 2016). "A decrease in LOX mRNA and/or protein has been observed in basal and squamous cell, bronchogenic, colon, esophageal, gastric, head and neck squamous cell, pancreatic and prostatic carcinomas, as well as melanoma." (PMID 23425977, 2013).